EYA4 (EYA transcriptional coactivator and phosphatase 4)
Diseases named in the same sentence as EYA4 in open-access papers (continued):
Sharing a sentence is not in itself a finding about the gene and the disease.
breast carcinoma (4 papers, 2014 to 2024). "Here, we show that over-expression of EYA4 increases proliferation and migration in breast cancer cells, features that are linked with aggressive breast cancer in vivo." (PMID 37292941, 2023). "Here, we demonstrate that EYA4 inhibits the expression of glycolytic genes, glucose uptake, and the production of lactate, pyruvate and ATP in liver cancer cells and breast cancer cells, suggesting that EYA4 is a repressor of glycolysis." (PMID 39617783, 2024). "Developing therapeutics aimed at the serine/threonine phosphatase activity of EYA4 represents a robust strategy for killing breast cancer cells, to limit metastasis and overcome chemotherapy resistance caused by endoreplication and genomic rearrangements." (PMID 37292941, 2023). "Consistent with this, our group and collaborators identified EYA4 as a potential novel breast cancer gene." (PMID 37292941, 2023). "Independent analysis indicated that EYA4 is statistically significantly over-expressed in breast carcinoma (P = 0.0440, Fisher's exact test)." (PMID 37777742, 2023). "Here, we show that EYA4 is over-expressed in breast cancer and that this increases proliferation and migration in breast cancer cells, features that are linked with aggressive breast cancer in vivo." (PMID 37777742, 2023). "This analysis also confirmed that EYA4 is over-expressed in breast carcinoma (P = 0.0286, Mann–Whitney U-test)." (PMID 37777742, 2023). "The function of EYA4 in promoting breast cancer growth and metastasis is also supported by in vivo xenograft studies showing that silencing of EYA4 expression in MDA-MB-231 cells leads to reduced cancer burden and distant metastasis." (PMID 37292941, 2023). "EYA4 is an important novel breast cancer gene and prognostic marker, with the potential to be a valuable diagnostic and therapeutic target for triple-negative breast cancer." (PMID 37292941, 2023). "Altogether, our data suggest that EYA4 is a driver of breast cancer and that decreasing its expression reduces tumor and metastatic burdens." (PMID 37292941, 2023). "Taken together, our data indicate that EYA4 is a novel potential breast cancer oncogene that supports primary tumor growth and metastasis." (PMID 37777742, 2023). "In the present study, we found that the over-expression of EYA4 in breast tissue leads to an aggressive and invasive breast cancer phenotype, while the inhibition of EYA4 reduced tumorigenic properties of breast cancer cells in vitro and in vivo." (PMID 37292941, 2023). "Taken together, our data indicate that EYA4 is a novel breast cancer oncogene that supports primary tumor growth and metastasis." (PMID 37292941, 2023). "In this study, we used HeLa and breast cancer cell lines to investigate the proliferation rates of cells knocked down or over-expressing EYA4, ex vivo and as xenografts in small animals." (PMID 37292941, 2023). "These two xenograft studies suggest that EYA4 therapeutic targeting is an interesting avenue that should be pursued for anti-breast cancer drug development." (PMID 37292941, 2023). "EYA4 over-expression leads to a more aggressive breast cancer, as observed by immunohistochemistry (IHC) staining." (PMID 37292941, 2023). "Taken together, our data indicate that EYA4 is a novel oncogene in breast cancer and could play a role in cell cycle maintenance." (PMID 37292941, 2023). "Thus, EYA4 is over-expressed in breast carcinoma at the protein level and this is reflected in the MDA-MB-231 cell line." (PMID 37777742, 2023). "Ultimately, this requires further investigation in order to understand the consequences of gene expression, and in the present study, we found that EYA4 is significantly over-expressed in breast carcinoma compared to normal breast tissue, using immunohistochemistry analyses." (PMID 37777742, 2023). "We also assessed whether EYA4 is over-expressed in breast cancer tissues by immunohistochemistry using an orthogonally validated EYA4-specific antibody." (PMID 37777742, 2023).
breast carcinoma (continued). "Cellular changes downstream of EYA4, including cell proliferation and migration, may explain the increased metastatic power of breast cancer cells over-expressing EYA4." (PMID 37292941, 2023). "The S/T phosphatase domain of EYA4 contributes to breast cancer development." (PMID 37292941, 2023). "Taken together, our data indicate that EYA4 is a potential novel oncogene in breast cancer and could play a role in cell cycle maintenance." (PMID 37777742, 2023). "We investigated whether EYA4 is expressed in breast cancer cell lines of various subtypes using real-time quantitative PCR and immunoblotting." (PMID 37777742, 2023). "We compared EYA4 expression in 3 normal breast epithelial tissues to 12 breast carcinoma tissues." (PMID 37777742, 2023). "Importantly, we have shown that the serine/threonine phosphatase activity of EYA4 is important for breast cancer progression and metastasis, suggesting that targeting the EYA4 phosphatase activity could help devise new cancer treatments directed against primary tumors and distant metastasis." (PMID 37292941, 2023). "However, EYA4 is the least well-characterized member of this unique family of PP, with its biological functions and molecular mechanisms in cancer progression, particularly in breast cancer, still largely unknown." (PMID 37777742, 2023). "However, EYA4 is the least wellcharacterized member of this unique family of phosphatases, with its biological functions and molecular mechanisms in cancer progression, particularly in breast cancer, still largely unknown." (PMID 37292941, 2023). "Interestingly, we found that the serine/threonine phosphatase activity of EYA4, but not its tyrosine phosphatase, is essential for breast cancer progression and metastasis." (PMID 37292941, 2023).
glioma (4 papers, 2011 to 2024). A benign or malignant brain and spinal cord tumor that arises from glial cells (astrocytes, oligodendrocytes, ependymal cells). "In nervous system tumors like glioma and malignant peripheral nerve sheath tumor, EYA4 functions as an oncogene." (PMID 39617783, 2024). "Our data are in line with previous observations in glioma where EYA4 over-expression promotes cell proliferation by directly suppressing the expression of p27KIP1, suggesting p27KIP1 as a transcriptional target of EYA4." (PMID 37777742, 2023).
esophageal cancer (3 papers, 2009 to 2022). A primary or metastatic malignant neoplasm involving the esophagus. "The testing sensitivities in the predicting ESCD and ESCC in the discriminant model including EYA4 and hTERT and the five traditional risk factors (sex, age, smoking, alcohol drinking, and family history of esophageal cancer) were 70% and 80%, and testing specificities were 76% and 88% respectively." (PMID 19939248, 2009). "EYA4 is frequently hypermethylated and down-regulated in colon and esophageal cancers." (PMID 22493696, 2012). "Multinomial logistic regression analysis gave odds ratios (ORs) for EYA4 and hTERT mRNA expression also increased with the severity of the diseases after adjustment for age, gender, smoking index, drinking index and family history of esophageal cancer." (PMID 19939248, 2009).
esophageal squamous cell carcinoma (3 papers, 2009 to 2024). Esophageal squamous cell carcinoma (ESCC) is a type of esophageal carcinoma (EC) that can affect any part of the esophagus, but is usually located in the upper or middle third. "However, to our knowledge, no reports have yet linked expression of the EYA4 gene linkage with esophageal squamous cell carcinoma (ESCC)." (PMID 19939248, 2009).
otitis media (3 papers, 2012 to 2015). Inflammation of the anatomical structures of the middle ear, which is most often caused by an infectious process. "It was reported Eya4-deficient mice developed heritable otitis media, which indicated that Eya4 regulation is critical for the development and function of the middle ear cavity and eustachian tube." (PMID 25961296, 2015). "Eya4-deficiency leads to Eustachian tube dysfunction and renders the mice susceptible to otitis media." (PMID 22539951, 2012). "Previous candidate gene studies associated a number of immune system genes with otitis media, which included TNF-α, IL-6, IL-10, Tlr4, surfactant, CD14, FcγRIIa, IFNγ, Eya4, p73, MyD88, Fas, E2f4, Plg, Fbxo11, and Evi1." (PMID 24466073, 2014).
otitis media with effusion (3 papers, 2013 to 2021). Otitis media associated with accumulation of fluid in the middle ear. "EYA4 knockout mice suffer from serious hearing loss and secretory otitis media, and malformations of the tympanic cavity and auditory tube were found in anatomical studies." (PMID 25961296, 2015). "Eya4-deficient mice exhibit Eustachian tube dysmorphology and otitis media with effusion which is not present in DFNA10 humans." (PMID 34847940, 2021).
pancreatic ductal adenocarcinoma (3 papers, 2018 to 2023). An infiltrating adenocarcinoma that arises from the epithelial cells of the pancreas. "Our recent study demonstrated that EYA4 is silenced in pancreatic ductal adenocarcinoma (PDAC) and forced expression of EYA4 can block nuclear β-catenin inclusion and Id2 transcription to oppose PDAC development." (PMID 36741265, 2023). "Our previous study also revealed that EYA4 expression is repressed in human pancreatic ductal adenocarcinoma and mediates tumor-suppressive effects by abolishing the β-catenin Ser675-dependent transactivation of inhibitor of DNA binding 2 (ID2)." (PMID 29764501, 2018). "Eyes absent homologue 4 (EYA4) is silenced in pancreatic ductal adenocarcinoma (PDAC) and functions as a tumor suppressor to restrain PDAC development, albeit the molecular mechanism underlying its downregulation remains enigmatic." (PMID 36741265, 2023). "Because our previous studies demonstrated that EYA4 dephosphorylates β-catenin Ser675 in human pancreatic ductal adenocarcinoma, we explored whether β-catenin Ser675 dephosphorylation is instrumental for RAP1 repression by EYA4 in HCC." (PMID 29764501, 2018).
colon cancer (2 papers, 2010 to 2011). "Somatic mutation of NTRK3 has been reported in human colon cancer, while methylation of EYA4 has been documented previously in ulcerative colitis-associated dysplasia and CRC." (PMID 20492682, 2010).
non-small cell lung carcinoma (2 papers, 2019 to 2023). A group of at least three distinct histological types of lung cancer, including non-small cell squamous cell carcinoma, adenocarcinoma, and large cell carcinoma. "Hypermethylation and reduced expression of EYA4 have been observed in both major subtypes of non-small cell lung cancer and even in the initial stages of the disease." (PMID 37156847, 2023).
pancreatic cancer (2 papers, 2018 to 2023). "Here we conduct a cancer cell line encyclopedia (CCLE)-based screen across 40 genes encoding E3 ligase in 12 pancreatic carcinoma cell lines to identify the candidate whose expression is inversely correlated with EYA4." (PMID 36741265, 2023). "In another study, we revealed that the tumor-suppressive role of EYA4 in pancreatic tumor growth relies on repression of the transactivation of ID2 via β-catenin Ser675 phosphorylation." (PMID 29764501, 2018).
triple-negative breast carcinoma (2 papers, 2023). An invasive breast carcinoma which is negative for expression of estrogen receptor (ER), progesterone receptor (PR), and human epidermal growth factor receptor 2 (HER2). "Specifically, our observation that EYA4 is hypermethylated in the first intron-exon junction particularly in triple-negative breast cancer patients when compared to matched normal samples, led us to pursue its role in carcinogenesis and its cellular functions." (PMID 37292941, 2023). "This makes EYA4 an attractive druggable target in cancer treatments, especially in triple-negative breast cancer, to limit metastasis and overcome chemotherapy resistance." (PMID 37292941, 2023). "The expression of EYA4 varied greatly across cell lines, however, the triple-negative breast cancer cell line MDA-MB-231 showed the highest endogenous expression of EYA4." (PMID 37292941, 2023). "In triple-negative breast cancer xenografts, the knockdown of EYA4 was able to efficiently limit the spread of metastasis and the overall cancer burden." (PMID 37292941, 2023). "EYA4 level is inversely correlated with ER status, with high expression largely found in triple-negative breast cancer, while ER+ tumors and cell lines express little or no EYA4." (PMID 37292941, 2023).
holoprosencephaly (1 paper, 2011). Holoprosencephaly (HPE) is a complex brain malformation resulting from incomplete cleavage of the prosencephalon, occurring between the 18th and 28th day of gestation, and affecting both the forebrain and face, which results in neurological manifestations and facial anomalies of variable severity. "Eya4 and Six3 have been demonstrated to interact in a study of holoprosencephaly, indicating that Eya4 may be the functional bridge between Six3 and Six3OS in the developing ventral forebrain." (PMID 21936910, 2011).
inflammatory bowel disease (1 paper, 2023). A spectrum of small and large bowel inflammatory diseases of unknown etiology. "Indeed, inflammatory bowel disease (IBD) increases the risk of colorectal cancer when methyl groups are covalently bound to cytosines in the CpG islands in stool DNA, specifically in loci containing BMP3, VIM, EYA4 and DRG4 genes." (PMID 38299096, 2023).
liver cancer (1 paper, 2024). An epithelial or non-epithelial malignant neoplasm that arises from the liver. "ERK1/2 expression is positively correlated with pS225 and EYA4 expression is negatively associated with pS225 in liver cancer specimens." (PMID 39617783, 2024).
lobular breast carcinoma (1 paper, 2023). "In addition, we observed that EYA4 expression is significantly higher in ductal than in lobular breast carcinomas (P = 0.0326, t-test), consistent with the observation that the 5-year mortality rate is significantly poorer for ductal than for lobular breast carcinoma patients." (PMID 37777742, 2023).
lymph node metastases (1 paper, 2016). "Multivariate analysis showed that EYA4 protein level, tumor number, adjacent organ invasion, lymph node metastasis, and tumor tumor differentiation were independent prognostic factors for DFS and OS." (PMID 27469137, 2016). "Univariate analysis showed that EYA4 protein level, serum CA19-9 level, serum CEA level, tumor number, adjacent organ invasion, lymph node metastasis, and tumor differentiation were prognostic factors for DFS and OS." (PMID 27469137, 2016). "Furthermore, tumors with lymph node metastases had a lower EYA4 protein level than tumors without lymph node metastases, with a median IHC score of 3.2 (range, 0.7–6.5) vs 3.6 (range, 2.0–6.6; P < 0.001)." (PMID 27469137, 2016).
melanoma (1 paper, 2014). A malignant, usually aggressive tumor composed of atypical, neoplastic melanocytes. "Our group performed a Tiling Array CGH, and, apart from highlighting common CN losses and amplification in the subgroups of primary melanomas, we demonstrated that 6q12–6q25.1 comprises a remarkable CN loss, harbouring two hypermethylated genes on 6q23, EYA4 and MYB1." (PMID 24832207, 2014).
metastasis (1 paper, 2016). The spread or migration of cancer cells from one part of the body (where they first appeared) to another. "Univariate and multivariate analyses showed that EYA4 protein level, tumor number, adjacent organ invasion, lymph node metastasis, and tumor differentiation were independent prognostic factors for disease-free survival and overall survival (all P < 0.05)." (PMID 27469137, 2016).
non-syndromic autosomal dominant deafness 10 (1 paper, 2021). "Eya4 expression was determined in the cochlea of the common marmoset due to the phenotypic discrepancies between Eya4-deficient mice and humans with EYA4 linked non-syndromic autosomal dominant deafness 10 (DFNA10)." (PMID 34847940, 2021).
rectal cancer (1 paper, 2016). A primary or metastatic malignant neoplasm that affects the rectum. "Ten of the 36 (EYA4, FOXI2, CNRIP1, SFRP1, ADHFE1, C2orf40, MAL, PHACTR3, SST, TMEFF2) were known as rectal cancer related genes with aberrant methylation." (PMID 27566576, 2016).